REN (renin)
Diseases named in the same sentence as REN in open-access papers (continued):
Sharing a sentence is not in itself a finding about the gene and the disease.
Hypertension (continued). "To evaluate participation of (pro)renin/renin receptor, a receptor of RAAS participating in hypertension, we administered HRP." (PMID 38629095, 2024). "Based on these observations, a new model of generation of SS hypertension was proposed, in which NaCl load disrupts the mechanism of reducing TPR in SS and/or low-renin forms of monogenic hypertension." (PMID 37700113, 2024). "High systemic androgen levels lead to increased sodium reabsorption through activation of the renin–angiotensin–aldosterone system (RAAS), leading to hypertension and increased intra-renal pressure." (PMID 39410601, 2024). "Renin initiates a cascade of events in the RAS, leading to the generation of angiotensin II, which stimulates AT1R to induce hypertension." (PMID 39203744, 2024). "We investigated the effects of commonly used antihypertensive drugs on the plasma aldosterone concentration (PAC), direct renin concentration (DRC), and ARR of patients with PA and essential hypertension (EH)." (PMID 38536656, 2024). "Then the renin acts on the angiotensinogen to produce angiotensin I (Ang I), which is transformed by the ACE into angiotensin II (Ang II), the major player in hypertension." (PMID 38345042, 2024). "A standardized herbal medicinal product containing roselle has effectively reduced blood pressure, lowered triglycerides, and decreased mean serum renin and ACE activity in patients with grade 1 essential hypertension." (PMID 39273041, 2024). "In experimental models, VEGF-TKIs correlate with a decrease in renin activity, but angiotensin-converting enzyme (ACE) inhibitors have a limited impact on hypertension compared with Ca2+-channel blockers." (PMID 36836722, 2023). "Hypertension and NAFLD contribute to each other's progression, and the mechanisms of this interaction are insulin resistance, activation of the renin–angiotensin–aldosterone system and the sympathetic nervous system, and arterial stiffness." (PMID 38162856, 2023). "The literature has additionally suggested this connection to the renin-angiotensin-aldosterone system (RAAS), a determinate in hypertension, a cardiometabolic phenotype." (PMID 37432296, 2023). "Regarding hypertension, high SUA levels have been shown to lead to renal vasoconstriction mediated by a decrease in endothelial nitric oxide and the activation of the renin-angiotensin system." (PMID 38169712, 2023). "The patient had hypertension, hypokalemia, and PAC > 15 ng/mL, aldosterone to renin ratio (ARR) > 30, with a positive captopril test and a combination of unilateral adrenal enlargement, she was diagnosed PA." (PMID 38013303, 2023). "There is some evidence that the renin-aldosterone-angiotensin system and sympathetic nervous system appear to be altered in TS and therefore we suggest hypertensive agents targeting these systems may have a beneficial role in treatment of hypertension in these patients." (PMID 36471031, 2023). "The pathophysiology of hypertension in THR involves mechanisms such as reduced NO production, dysregulation of the renin-angiotensin-aldosterone system, impaired endothelial function, and DIO2 gene mutations." (PMID 38174182, 2023). "The binding of renin to the PRR can also activate Ang II-independent pathways, thereby resulting in hypertension." (PMID 36771342, 2023). "Consistent with prior work showing the blocking of the classic RAS axis for the treatment of hypertension, GSNO-loaded nanoparticles protected against hypertension coinciding with the reduced expression of renin, ACE1, and AT1R in the kidneys." (PMID 36830071, 2023). "Another possible explanation is that angiotensin II (Ang II), the primary hormone of the renin-angiotensin system (RAS), plays a vital role in the pathophysiology of hypertension." (PMID 37840913, 2023). "In animal studies, aprocitentan resulted in a dose-dependent decrease in BP in two animal models with hypertension: DOCA-Salt rats (low-renin model) and spontaneously hypertensive rats (SHR) (normal-renin model)." (PMID 36983961, 2023).
Hypertension (continued). "Patients in the renin-angiotensin system inhibitors (RASi) group were older and had a higher percentage of males, lower percentage of ECOG score 0, higher percentage of hypertension, and higher percentage of adenocarcinoma than those in the non-RASi group." (PMID 37901395, 2023). "Analysis from the CURE-CKD registry reported that a renin–angiotensin system inhibitor was prescribed to just 20.6% of patients overall, and to 20.5% of patients with CKD and hypertension." (PMID 35567698, 2023). "Despite several studies have reported low circulating renin levels in children with ARPKD, RAAS inhibitors are the most frequently medications used to treat hypertension and are efficient in most patients." (PMID 37006611, 2023). "Studies with vitamin D receptor (VDR) knockout mice show an increased renin–angiotensin–aldosterone system (RAAS) activity and increased hypertension, suggesting a key role for vitD as a potential antihypertensive agent." (PMID 36902110, 2023). "The mechanisms behind the development of hypertension in THR include reduced nitric oxide production, dysregulation of the renin-angiotensin-aldosterone system, impaired endothelial function, and mutations in the deiodinases." (PMID 38174182, 2023). "Two decades ago, new strain of inbred transgenic rats with inducible hypertension [strain name, TGR (Cyp1a1–Ren-2)] was generated using the cytochrome P-450 promoter, Cyp1a1, to regulate the expression of the mouse Ren-2 renin gene." (PMID 37389123, 2023). "New evidence suggests that improper activation of the renin-angiotensin system (RAS) and alterations in intestinal microflora are related to the pathogenesis of hypertension." (PMID 38029244, 2023). "Renin, ACE-1 and AT1R mRNA expression were significantly higher in patients with obesity and hypertension." (PMID 36973648, 2023). "The main effects of Renin-Angiotensin-Aldosterone System (RAAS) on cardiovascular system are atherosclerosis and hypertension, leading to congestive heart failure and MACCEs." (PMID 37270600, 2023). "Before we discuss the role of the Nrf2 in the modulation of central sympathetic nerve activity, it is also necessary to discuss the role of the renin-angiotensin system and reactive oxygen species in central sympathoexcitation in CHF and hypertension." (PMID 37719456, 2023). "NR3C1, REN, PPARG, and CYP11B1 were identified as critical targets (36-degree value) in the network for hypertension progression because of this conformity." (PMID 37571339, 2023). "Renal fibrosis with Renin–angiotensin–aldosterone system (RAAS) activation and oxidative stress are one of the major complications in hypertension." (PMID 37353787, 2023). "After exposure to natural xenobiotics such as indol-3-carbinol (I3C), the renin transgene is rapidly expressed primarily in the liver, leading to increased ANG II levels and the development of ANG II-dependent form of hypertension." (PMID 37389123, 2023). "Renin–angiotensin–aldosterone system (RAAS) blockers, which are used widely in most patients with pre-existing hypertension and diabetes, have also been postulated to increase the risk of developing more severe and fatal COVID-19 disease." (PMID 38131982, 2023). "The pathogenesis of hypertension is also well described by the renin-angiotensin system (RAS), which also provides the potential targets for the therapies against hypertension." (PMID 35204115, 2022). "All four patients that underwent plasma renin activity tests showed results below the reference range, but only the ALDO of case 1 is dramatically elevated, which accords with her hypertension and hypokalemia." (PMID 36589849, 2022). "Given the importance of the RAAS in the development of hypertension in SHRs, this may be a surprise, but the data are in line with previous studies showing that SHRs compared to normotensive rats have less renin expression in the kidney and release less renin into the circulation." (PMID 36552716, 2022).
Hypertension (continued). "T3 induce renin release and activate the renin-angiotensin-aldosterone system (RAAS), resulting in increased levels of angiotensin II signalling, hypertension and oxidative stress." (PMID 35239685, 2022). "It is well known that Ang II is one of the classic members of the renin-angiotensin-aldosterone system (RAAS), which participates in the development of hypertension." (PMID 35757324, 2022). "The prevalence of hypertension is higher in individuals with MAFLD, indicating an important relationship to systemic inflammation, insulin resistance, and activation of the renin-angiotensin-aldosterone and sympathetic autonomic nervous systems." (PMID 35668935, 2022). "Plasma aldosterone and renin levels and the ARR correlate with increased blood pressure and increased incidence of hypertension over time in the general population." (PMID 36057693, 2022). "In the PPI network, a total of 14 targets, such as TNF, CHRM1, ACE, IL10, PTGS2, REN, and F2, were the hub targets of MVO for treating hypertension." (PMID 35308213, 2022). "The general or classical renin–angiotensin system (RAS) is the endocrine league accountable for controlling various bodily and pathologic developments, such as hypertension, body water and electrolytic balance, and inflammation." (PMID 35625041, 2022). "Studies have shown that GAS can effectively intervene in the renin-angiotensin-aldosterone system (RAAS) and its resulting myocardial remodeling, thus playing a role in the treatment of hypertension." (PMID 35463081, 2022). "Hypertension in SHR is of multifactorial etiology, including an activated stress axis, sympathetic nervous system (SNS) and renin-angiotensin-aldosterone system (RAAS)." (PMID 36231118, 2022). "The pathophysiology of hypertension in OSA includes sympathetic tone, endothelial dysfunction, altered baroreceptor reflexes, and the increased renin-angiotensin-aldosterone system (RAS)." (PMID 36361741, 2022). "In diabetic nephropathy or Ang II-induced hypertension, for example, components of the RAS like angiotensinogen, ACE, (pro)renin, and AT1 receptors are upregulated along the nephron and in the medullary region leading to high levels of intratubular Ang II." (PMID 35511367, 2022). "Differentially methylated positions (DMPs) were assessed for plasma renin concentration, aldosterone, and ARR using linear regression models adjusted for age, sex, body mass index, diabetes mellitus, hypertension, and technical covariates." (PMID 36457109, 2022). "The complex interplay between the autonomic nervous system, renin-angiotensin-aldosterone system (RAAS), and immunity contributes to the pathogenesis of hypertension in diabetes mellitus." (PMID 35350513, 2022). "Hyperinsulinemia may induce renal sodium retention, renin-angiotensin system activation, enhanced sympathetic nervous system activity, endothelial cell dysfunction, and increased peripheral and renal vascular resistance, contributing to the development of hypertension." (PMID 35493612, 2022). "ACE is an integral part of the renin-angiotensin system (RAS) system, which can catalyze angiotensin I (Ang I) into Ang II with high-strength vasoconstriction activity, thereby inducing hypertension." (PMID 35600813, 2022). "Consequently, the presence of high renin arterial hypertension, which was found among most of the recipients in our cohort, may explain the lack of differences in the occurrence of CAD and PAOD between polymorphism carriers and noncarriers among patients undergoing dialysis." (PMID 36077181, 2022). "Among the known prohypertensive and profibrotic factors are the renin–angiotensin system (RAS), which is corrupted in the DSS rat model, and MBG, which participates in the development of hypertension in DSS rats." (PMID 35562955, 2022). "For that reason, RAAS inhibitors, such as direct renin inhibitors, ACE inhibitors, ARBs, and aldosterone antagonists, are often prescribed in the treatment of hypertension." (PMID 36430371, 2022).
Hypertension (continued). "The activation of renin-angiotensin system (RAS) including both the systemic RAS and the tRAS has long been considered an essential part during the development of hypertension." (PMID 36123994, 2022). "Previous studies suggest that increased renin and angiotensinogen (AGT) levels lead to an increased ANGII concentration, thereby stimulating hypertension and organ damage." (PMID 35203286, 2022). "Angiotensin II, an important hormone of the renin-angiotensin-aldosterone system (RASS), plays a crucial role in the pathogenesis of both hypertension and insulin resistance." (PMID 35350513, 2022). "Dysregulation of the renin-angiotensin-aldosterone system (RAAS) plays a pivotal role in the pathogenesis of hypertension, hypertension-induced target organ damage (TOD), CV events, and heat failure (HF)." (PMID 35369303, 2022). "Enzymes include angiotensin-I-converting enzyme (ACE-1; EC 3.4.15.1) and renin (EC 3.4.23.15), which operate within the renin–angiotensin–aldosterone (RAAS) system and control high blood pressure and salt-water balance." (PMID 35206049, 2022). "The renin-angiotensin system (RAS) serves as a potential guide for understanding the pathogenesis of SARS-CoV-2 infections, particularly in patients with hypertension." (PMID 34452063, 2021). "Hypertension can be controlled via inhibition of angiotensin-converting enzyme (ACE), the key enzyme in renin-angiotensin-aldosterone (RAAS) hormonal cascade." (PMID 33670795, 2021). "For COVID-19 patients with existing hypertension, the key targets and drugs are losartan, saralasin, telmisartan for targets AGTR1, AGTR2, and captopril for ACE and REN." (PMID 34067609, 2021). "Specifically, miR-181a was downregulated in a genetic model of massive SNS activation, leading to increased renin expression, RAAS activation, and consequently hypertension in mice." (PMID 34944415, 2021). "With the exception of renin, almost all components of the RAS system are expressed in PVAT, implying key roles in the regulation of hypertension-related perivascular inflammation." (PMID 34456867, 2021). "The bioinformatics analysis by the BIOPEP-UWM database showed possible effects to control hypertension through ACE and renin inhibition." (PMID 34681387, 2021). "Activation of the renin-angiotensin system is a significant mediator of NOX activation and ROS production in human hypertension." (PMID 34439468, 2021). "In mouse Ren-2 renin transgenic rats (TGR), hypertension depends on the constitutive expression of inserted and constantly activated transgenes." (PMID 34122103, 2021). "The renin-angiotensin-aldosterone (RAA) system is among the most important contributors to the pathogenesis of cardiovascular disease, including hypertension." (PMID 34945112, 2021). "ACE is an important enzyme in the renin-angiotensin system, and it is the target gene of ACE inhibitors, a common hypertension medication." (PMID 33541420, 2021). "Recently, inbred transgenic rats with inducible hypertension [strain name, TGR (Cyp1a1–Ren-2)] have been generated using the cytochrome P-450 promoter, Cyp1a1, to regulate the expression of the mouse Ren-2 renin gene." (PMID 34122103, 2021). "Despite the suppressed plasma renin activity (PRA) observed in these patients, treatment with RAS inhibitors slows the progression of hypertension." (PMID 34179130, 2021). "Binding of renin to the PRR can activate Ang II-dependent and -independent pathways, leading to hypertension." (PMID 33800916, 2021). "Our previous work showed DMF administration in pregnancy protects adult offspring against hypertension programmed by antenatal DEX plus postnatal high-fat diet, which was relevant to downregulated mRNA expression of renin, AGT, ACE, and AT1R." (PMID 33669059, 2021). "In addition, elevated renin levels are found in Eln+/− mice and 40%–50% of WS patients, which suggests that the renin-angiotensin system could be involved in a basal vessel constriction level and account for the featured hypertension." (PMID 35330621, 2021).
Hypertension (continued). "In the in silico study, the affinity of Criollo cocoa peptides for hypertension-related molecular targets ACE, renin, and AT1-R has been demonstrated." (PMID 34681387, 2021). "ACEI is a type of renin–angiotensin system (RAS) inhibitor and is commonly used to treat hypertension." (PMID 33430275, 2021). "Such enhanced expression of renin transgene results in an increase in ANG II levels and in the development of ANG II-dependent form of hypertension; the transgene expression and hypertension can be controlled in a dose-dependent and reversible manner." (PMID 34122103, 2021). "AngII is an effector molecule of the Renin–Angiotensin system (RAS), which plays a crucial role in hypertension in mammals." (PMID 34827169, 2021). "Interestingly, deletion of the renin-angiotensin system (RAS) genes — usually associated with hypotension — leads to an arterial phenotype indistinguishable from that observed in uncontrolled hypertension." (PMID 34762601, 2021). "Importantly, 4 serum metabolites were increased significantly, and 10 serum metabolites were decreased significantly across both hypertensive groups, one a low-renin model and the other a high-renin model, indicating that these may be important in the pathology of hypertension." (PMID 34572600, 2021). "Diabetes and hypertension share common pathways such as the sympathetic nervous system (SNS), renin-angiotensin-aldosterone system (RAAS), oxidative stress, adipokines, insulin resistance, and Peroxisome proliferator-activated receptors (PPARs)." (PMID 33669927, 2021). "Ang II, the key component of renin-angiotensin system (RAS), plays a vital role in mediating hypertension and cardiac hypertrophy." (PMID 34776960, 2021). "In ACEI-or ARB-treated patients with essential hypertension on monotherapy or combination therapy analyzed together (with exclusion of those receiving beta-blockers), PAC was decreased and renin levels were elevated, contributing to lower ARR." (PMID 34054559, 2021). "In our study, we have modeled the selected processes in a patient with essential hypertension and chronic kidney disease (CKD) suffering from COVID-19, emphasizing the function of the renin-angiotensin-aldosterone (RAA) system." (PMID 34638859, 2021). "The levels of plasma renin activity (PRA) and PAC decreased in response to rapid blood volume expansion and sodium loading in patients with essential hypertension during SIT." (PMID 33679972, 2021). "The pathophysiology of the cardiac consequences of CKD involves multiple factors, including hypertension, uremic toxins, FGF-23, and activation of the renin angiotensin aldosterone system." (PMID 32001792, 2020). "As a key element in the renin–angiotensin–aldosterone system (RAAS), ACE2 is critically involved in the pathophysiology of hypertension." (PMID 32631458, 2020). "In this model, RH is induced by partial unilateral renal artery occlusion, leading to renin secretion, RAAS over activation, development of arterial hypertension, cardiac hypertrophy, vascular remodeling, and kidney disease." (PMID 33145109, 2020). "Activation of RAS, such as high levels of serum Ang II, renin, ACE activity, and AT1R expression in LHR has been observed, and has contributed to hypertension and vascular remodeling in this animal model." (PMID 33007813, 2020). "The renin-angiotensin-aldosterone system (RAAS) plays a critical role in the initiation and development of hypertension." (PMID 32848742, 2020). "Activation of the renin–angiotensin system (RAS) is important in increasing peripheral resistance, which induces hypertension and plays a role in cerebrovascular disease." (PMID 32725211, 2020). "Regulation of renin-angiotensin-aldosterone system (RAAS)—RAAS is an important contributor to changes in arterial and cardiac stiffness, leading to hypertension and clinical heart failure." (PMID 32429489, 2020).